ZEB2 (zinc finger E-box binding homeobox 2)
Diseases named in the same sentence as ZEB2 in open-access papers (continued):
Sharing a sentence is not in itself a finding about the gene and the disease.
leukemia (continued). "Although SNAI1, ZEB1, and ZEB2 were not upregulated in RNA-seq data of Adh ALL patient samples, they have putative roles in leukemia development/progression, and we observed SNAIL (SNAI1) and ZEB1 but not ZEB2 to be highly expressed in Adh leukemic cell lines." (PMID 37453060, 2023).
liver cancer (17 papers, 2013 to 2025). An epithelial or non-epithelial malignant neoplasm that arises from the liver. "A great deal of evidence has shown that an abnormal expression level of ZEB2 is involved in several liver diseases, including liver cancer and hepatic fibrosis." (PMID 34421621, 2021). "Another study uncovered that miR-498 inhibited cell growth by regulating ZEB2 in patients with liver cancer." (PMID 34096776, 2021). "For instance, miR-222 hastens cell proliferation and migration of liver cancer through BBC3; miR-498 restrains the invasion and migration of liver cancer through ZEB2." (PMID 33959160, 2021). "Japanese scholar Yamada found that EMT‐induced transcription factors and mesenchymal markers Twist 1 and ZEB‐2 were significantly overexpressed in liver cancer, and patients with mesenchymal tumors were more likely to have early recurrence than those with epithelial tumors." (PMID 37676078, 2023). "For example, miR-1179 inhibits liver cancer metastasis by suppressing ZEB2 expression." (PMID 36193069, 2022). "MiR-200 could downregulate the expression of ZEB1 and ZEB2 in liver cancer, thereby inhibiting cell invasion and cancer progression." (PMID 36137140, 2022). "Additionally, a previous study has shown that miR-498 targets ZEB2 to inhibit invasion, migration, and proliferation in liver cancer cells, suggesting that the level of ZEB2 is abnormal in some diseases, including liver disease." (PMID 34421621, 2021). "LncRNA-ATB has been reported to be an endogenous “sponge” that upregulates ZEB1 and ZEB2 by competitively binding to the miR-200 family, thereby inducing EMT and liver cancer invasion." (PMID 33552968, 2020). "In addition, miR-203 downregulation has been described in various cancers including esophagus, cervix, prostate, breast, and liver cancer, and miR-203 inhibits cancerous invasion by targeting SNAI1, SNAI2, ZEB2, and VEGFA." (PMID 26882562, 2016).
Hirschsprung disease (16 papers, 2007 to 2025). Hirschsprung disease (HSCR) is a congenital intestinal motility disorder that is characterized by signs of intestinal obstruction due to the presence of an aganglionic segment of variable extent in the terminal part of the colon. "Of these genes, LAMA4, ZEB2, CTNNAL1, ITGA6 and ITIH5 have previously been associated with Hirschsprung’s disease and ZEB2 was shown to genetically interact with SOX10." (PMID 39982575, 2025). "Germline de novo ZEB2 mutations or deletions cause a dominant syndromic form of Hirschsprung disease (HSCR) called Mowat-Wilson Syndrome." (PMID 37600794, 2023). "In a screening for copy number variants in genes related to Hirschsprung Disease, four patients have been described with ZEB2 duplications of part of exon 1 and all of exon 2, ranging from 1.42 to 1.99 kb." (PMID 32628253, 2020). "Patients with a deletion of the whole ZEB2 gene also had similar abnormalities (tetralogy of Fallot, agenesis of the corpus callosum, Hirschsprung disease)." (PMID 33982229, 2021). "Mice with conditional Zeb2 knockout in these regions have a reduced development of visceral motor neurons, which leads to Hirschsprung disease." (PMID 34199024, 2021). "Mice with conditional Zeb2 knockout in these regions have a reduced development of visceral motor neurons, which could lead to Hirschsprung disease." (PMID 34199024, 2021). "The field also studied compound Zeb1;Zeb2 mutant mice for few sites in the embryo where their presence overlaps, i.e., in somitogenesis, as well as compound Zeb2+/− mutant mice with other mutant mice for Hirschsprung disease genes in order to study NCC-derived ENS cells." (PMID 34356053, 2021). "Furthermore, the transcription factor Smad-interacting protein 1 (also known as SIP1 or ZEB2), a negative regulator of BMP4 signaling, is involved in the specification, differentiation, and migration of neural crest cells, and mutations in this gene are associated with Hirschsprung disease." (PMID 37958648, 2023).
glioblastoma (14 papers, 2017 to 2025). The most malignant astrocytic tumor (WHO grade IV). "qRT-PCR showed significant upregulation of mesenchymal glioblastoma markers (>100-fold ZEB2; >10-fold TWIST1; FN1, <10-fold VIM; ZEB1; *p < 0.01) in KW10 cells as compared to MTA10 cells." (PMID 28744448, 2017). "Therefore, we concluded that KDELC2 promotes glioblastoma angiogenesis by upregulating ZEB2, VEGF-A, VEGF-R1, and PDGFA expression." (PMID 37107298, 2023). "COBL is an actin nucleator involved in neurite outgrowth and of particular importance to proper cerebellum formation and ZEB2 is a zinc finger E-box binding transcription factor that plays a role in promoting migration and invasion of both adult and pediatric glioblastoma cells." (PMID 35590427, 2022). "The effect of miR-203 (the commonly used name of miR-203a-3p) on ZEB1 and ZEB2 genes was previously shown in many cancer types, such as lung, gastric, cervical, prostate, colon, and renal cancers, as well as glioblastoma, cholangiocarcinoma, and nasopharyngeal carcinoma, for both ZEB1 and ZEB2." (PMID 35163224, 2022). "In addition, miR-637 retards glioblastoma progression via the ZEB2/WNT/beta-catenin cascades." (PMID 36329557, 2022). "For example, miR-590-3p reduced migration, invasion and EMT in glioblastoma multiforme by targeting ZEB1 and ZEB2, and in intrahepatic cholangiocarcinoma by targeting ZEB2." (PMID 37138218, 2023). "However, it is proposed in glioblastoma that high MSH6 promotes aggressive cell phenotypes more directly by acting through a MSH6-CXCR4-TGFβ1 feedback loop that regulates p-STAT3/Slug and p-Smad2/3/ZEB2 signalling pathways." (PMID 36482191, 2023). "For example, in glioblastoma (and possibly other tumor types), the glycoprotein Epsin3 (EPN3) may be related to Notch and WNT/β-catenin signaling pathways, and helps to induce EMT in glioblastoma cells after activating SLUG, TWIST, and ZEB1, but not Snail1 or ZEB2." (PMID 33430387, 2021).
osteosarcoma (14 papers, 2017 to 2024). A usually aggressive malignant bone-forming mesenchymal neoplasm, predominantly affecting adolescents and young adults. "The newly identified miR-101/ZEB2 link offers a new insight into the mechanisms underlying osteosarcoma development, and provides a promising therapeutic strategy for osteosarcoma treatment in the future." (PMID 30692230, 2019). "SPRY4-IT1 can also regulate the expression of ZEB1 and ZEB2 by sponge miR-101 activity, thereby promoting the progression of osteosarcoma." (PMID 39015175, 2024). "In summary, lncRNA SCAMP1 modulated the expression of ZEB2 via sponging miR-26a-5p in osteosarcoma, which resulted in promotion of viability and colony formation of osteosarcoma cells." (PMID 35992869, 2022). "We also reported that lncRNA SCAMP1 promoted cell invasiveness and migrative capacity in osteosarcoma cells via regulating miR-26a-5p/ZEB2 axis." (PMID 35992869, 2022). "In a word, lncRNA SCAMP1 regulated cell invasiveness and migrative ability through targeting miR-26a and ZEB2 pathways in osteosarcoma." (PMID 35992869, 2022). "We dissected that lncRNA SCAMP1 promoted progression of osteosarcoma via modulation of miR-26a-5p/ZEB2 axis." (PMID 35992869, 2022). "In our study, we reported that lncRNA SCAMP1 modulated the expression of ZEB2 via sponging miR-26a-5p in osteosarcoma, which led to promotion of cell viability and colony formation." (PMID 35992869, 2022). "Forced expression of microRNA-187 inhibits EMT progression in osteosarcoma by directly targeting the 3′UTR of ZEB2." (PMID 32149094, 2020). "To explore the potential functions of ZEB2 in osteosarcoma, we co-transfected the G292 cells with pc-ZEB2 or miR-101." (PMID 30692230, 2019). "The expression of ZEB2 mRNA was significantly higher in osteosarcoma cell lines (including U2OS, G292, MG63, SJSA2, and KHOS) than those from normal human osteoblast cell line HOB-c." (PMID 30692230, 2019). "As the results showed, it was found that ZEB2 was significantly up-regulated in osteosarcoma tissues when compared with the adjacent normal tissues." (PMID 30692230, 2019). "The expression of ZEB2 in osteosarcoma tissues and adjacent normal tissues were then detected using qPCR assays." (PMID 30692230, 2019). "Our studies illustrated that miR-101 suppressed osteosarcoma progression via ZEB2, which contributed a better understanding of ZEB2 on osteosarcoma." (PMID 30692230, 2019). "MiR-101 has been proved to be down-regulated in osteosarcoma and has the ability to suppress osteosarcoma cell proliferation and invasion by directly targetting ZEB2." (PMID 30692230, 2019). "t has been shown that ZEB2 is overexpressed in osteosarcoma." (PMID 38652223, 2024). "Moreover, lncRNA SCAMP1 performed their functions on cell motility via targeting miR-26a-5p/ZEB2 axis in osteosarcoma." (PMID 35992869, 2022). "Since ZEB2 is the critical driver in EMT progression, it is needed to address whether lncRNA SCAMP1 can regulate the EMT in osteosarcoma via targeting ZEB2." (PMID 35992869, 2022). "In conclusion, targeting lncRNA SCAMP1 and its downstream targets, miR-26a-5p and ZEB2, might be a useful approach for osteosarcoma therapy." (PMID 35992869, 2022). "Moreover, from the transwell assays, it is confirmed that the inhibition of cell invasion by miR-101 was greatly rescued by ZEB2 overexpression in osteosarcoma cell." (PMID 30692230, 2019). "The results demonstrated that the miR-101/ZEB2 axis may be a promising therapeutic strategy for osteosarcoma treatment in the future." (PMID 30692230, 2019). "Furthermore, it is demonstrated, for the first time, that the miR-101/ZEB2 axis plays an essential role in regulating osteosarcoma proliferation and metastasis." (PMID 30692230, 2019). "Additionally, miR-101 is significantly down-regulated in osteosarcoma and could inhibit the proliferation and invasion of osteosarcoma by targeting ZEB2." (PMID 36497343, 2022). "Altogether, miR-26a-5p could target ZEB2 in osteosarcoma cells." (PMID 35992869, 2022).
osteosarcoma (continued). "In addition, overexpression of ZEB2 could rescue the inhibition effect of proliferation and invasion induced by miR-101 in osteosarcoma cells." (PMID 30692230, 2019). "Moreover, we tested whether lncRNA SCAMP1 regulated the expression of ZEB2 in osteosarcoma cells." (PMID 35992869, 2022). "In osteosarcoma, ZFAS1 was observed directly interacting with ZEB2 protein and then regulated the stability of ZEB2, thereby leading to increased cell growth and metastasis." (PMID 33202381, 2020). "Through BMI1 and ZEB2, ZFAS1 regulates osteosarcoma cell growth and metastasis." (PMID 35184675, 2022). "Downregulation of GAS5 in hFOB 1.19 and U2OS osteosarcoma cells enhanced their migration and invasion, along with an upregulated epithelial–mesenchymal transition (EMT), as evidenced by downregulated E-cadherin and upregulated vimentin, ZEB1, and ZEB2." (PMID 34386496, 2021). "Furthermore, qPCR assays showed that miR–101 overexpression decreased the mRNA expression of ZEB2 in G292 and U2OS cells, which illustrated that miR–101 directly targetted ZEB2 by binding to its 3′–UTR region in osteosarcoma cells." (PMID 30692230, 2019).
lung adenocarcinoma (13 papers, 2016 to 2025). A carcinoma that arises from the lung and is characterized by the presence of malignant glandular epithelial cells. "Previous studies also reported that the Wnt/β-catenin pathway contributes to the induction of EMT by transactivating several EMT-related transcriptional factors, such as Snail, Slug, Twist, ZEB1, and ZEB2 in lung adenocarcinoma." (PMID 34497759, 2021). "Additionally, miR-138-5p, down-regulated in lung adenocarcinoma tissues and cells, was ascertained to repress metastasis via targeting ZEB2." (PMID 35101035, 2022). "Importantly, YAP1 activation in lung adenocarcinoma has been shown to induce ZEB2 expression." (PMID 41002380, 2025). "Induction of EMT by RGCC in A549 lung adenocarcinoma cells occurs through the activation of NF-κB signaling pathway, whereas in colon adenocarcinoma cells, RGCC activates the Smad/Zeb2 pathway." (PMID 34015051, 2021). "Additionally, miR-138-5p was identified to bind directly to ZEB2, and decreased ZEB2 to suppress the EMT process, proliferation, and metastasis of lung adenocarcinoma cells." (PMID 34299149, 2021). "As CBX4 suppresses LUAD metastasis through transcriptional inhibition of ZEB2, activating the expression of CBX4 together with blocking the interaction between CBX4 and GCN5 in lung adenocarcinoma cells can inhibit the metastasis of LUAD without affecting tumor cell proliferation." (PMID 38816356, 2024). "In contrast, expression levels of the remaining factors were not different between tumours and normal tissues (ZEB2, SNAI1 and SLUG), or even higher in tumours (TWIST), implying that these factors may not be the primary regulators of EMT in lung adenocarcinomas." (PMID 27456471, 2016).
cervical cancer (12 papers, 2017 to 2024). A primary or metastatic malignant neoplasm involving the cervix. "Hsa-miR-200a has been shown to downregulate metastatic genes such as ZEB1, and ZEB2, which is suggested to suppress the migration of cervical cancer cells." (PMID 36879084, 2023). "A novel lncRNA CTS identified from the lncRNA microarray database was found to promote metastasis and EMT of cervical cancer by regulating miR-505/ZEB2 axis." (PMID 33777808, 2021). "Circ_0001247 induces cervical cancer by regulating ZEB2 via sponging miR-1270." (PMID 39039600, 2024). "Moreover, similar to Snail1 in cervical cancer, ZEB2 also binds to PRMT5 and the NuRD complex to form a multimeric transcriptionally repressive unit." (PMID 35884488, 2022). "LncRNA CTS, therefore, stimulates ZEB2-mediated EMT through miR-505 sponging, leading to the enhanced viability, proliferation, and malignancy of cervical cancer cells." (PMID 32664703, 2020). "Meanwhile, circNRIP1 also increased ZEB2 expression and decreased E-cadherin expression in CC cells, indicating that circNRIP1 was also involved in EMT in cervical cancer." (PMID 32457332, 2020). "MiR-505 down-regulates ZEB2 levels to inhibit EMT and invasion of cervical cancer cells." (PMID 32664703, 2020).
epilepsy (12 papers, 2013 to 2024). A brain disorder characterized by episodes of abnormally increased neuronal discharge resulting in transient episodes of sensory or motor neurological dysfunction, or psychic dysfunction. "One of the samples with a low MVP score corresponds to the only individual with a ZEB2 missense variant included in this cohort (#2), who also presented with a mild phenotype withouth epilepsy." (PMID 38351292, 2024). "Mutations in TCF4, MEF2C, UBE3A, ZEB2 or ATRX cause phenotypically overlapping, syndromic forms of NDDs with severe intellectual disability, epilepsy and microcephaly." (PMID 31988313, 2020). "DNA of the proband’s father was not available since he passed away prior to the analysis, therefore WES was performed only on the girl’s DNA and identified two heterozygous variants in two different epilepsy-associated genes, CACNB4 (NM_000726.5) and ZEB2 (NM_014795.4)." (PMID 36360260, 2022).
nasopharyngeal carcinoma (12 papers, 2013 to 2025). A carcinoma arising from the nasopharyngeal epithelium. "In another investigation, miR-203 was reported modulating tumor stemness and chemotherapy resistance in nasopharyngeal carcinoma by interacting with ZEB2." (PMID 28982387, 2017). "The miR-200a was observed regulates epithelio-mesenchymal to stem-like transition in nasopharyngeal carcinoma cells by targeting ZEB2 and ß-catenin signaling genes." (PMID 23936298, 2013). "explored the involvement of the DNMT1/miR‐142‐3p/ZEB2 axis in nasopharyngeal carcinoma (NPC)." (PMID 40387409, 2025). "In nasopharyngeal carcinoma, miR-142-3p was downregulated by DNA methylation due to EZH2’s recruitment of DNMT1 which occupied the upstream region of the miR-142 and determined ZEB2 activation, leading to EMT and metastasis." (PMID 33014831, 2020). "It was noted that interactions of miR-203 with ZEB1 and ZEB2 suppressed metastasis and EMT in multiple cancers and, in addition, antimetastatic miR-203, inhibiting ZEB2, reduced tumor stemness and chemotherapy resistance, for example, in nasopharyngeal carcinoma." (PMID 35163224, 2022).
renal carcinoma (12 papers, 2015 to 2024). A carcinoma arising from the epithelium of the renal parenchyma or the renal pelvis. "MiR-153 was found to exert inhibitory impact on ZEB2 expression to suppress renal cancer, while circPCNXL2 stimulates ZEB2 expression via miR-153 sponging to elevate the invasion and proliferation of renal cancer cells." (PMID 32664703, 2020). "Cotransfection of miR-124 and miR-203 into 786-O cell lines effectively attenuated ZEB2 level and normalized renal cancer cell proliferation and migration." (PMID 32046742, 2020). "In a recent study, MALAT1 was found to compete with endogenous RNA to regulate ZEB2 expression by sponging with miR-200 s in kidney carcinoma." (PMID 30098599, 2018). "In renal carcinoma cell lines, overexpression of miR-141 resulted in downregulation of ZEB2 and upregulation of E-cadherin." (PMID 25975736, 2015). "Also, miR-153 can be targeted by CircPCNXL2, which overexpresses ZEB2 in renal carcinoma in a manner dependent on the CircPCNXL2/miR-153/ZEB2 axis." (PMID 36158686, 2022). "A study demonstrated that honokiol could increase miR-141 expression and further down-regulate the target gene zinc finger E-box binding homeobox 2 (ZEB2) in renal cancer cells." (PMID 26305257, 2015). "Therefore, decreasing the expression of circPCNXL2 may yield an up-regulation of miR-153 and suppresses ZEB2 expression to eliminate renal cancer." (PMID 32664703, 2020). "We also found a positive correlation between PVT1 and BMI1, ZEB1 and ZEB2 as well as a negative correlation between miR-200c and PVT1, BMI1, ZEB1 and ZEB2 in our 50 paired renal cancer tissues through RT-PCR, which was consistent with that of the analysis from TCGA Data Portal." (PMID 29156724, 2017).